GCNT3 (glucosaminyl (N-acetyl) transferase 3, mucin type)
Description:
Glycosyltransferase that can synthesize all known mucin beta 6 N-acetylglucosaminides. Mediates core 2 and core 4 O-glycan branching, 2 important steps in mucin-type biosynthesis. Also has I-branching enzyme activity by converting linear into branched poly-N-acetyllactosaminoglycans, leading to introduce the blood group I antigen during embryonic development.
Synonyms: C2GnT-M; C2/4GnT; C2GnT2; C24GNT; C2GNTM; GNTM
Tractability: Antibody: UniProt predicts a signal peptide or a membrane-spanning region.
Gene: Protein-coding gene on chromosome 15 (59,594,875 to 59,640,239, forward strand). Ensembl gene ENSG00000140297.
Subcellular location: Golgi apparatus membrane
Subcellular location (Human Protein Atlas): Golgi apparatus; Vesicles
Pathways (Reactome):
Metabolism of proteins: O-linked glycosylation of mucins
Gene Ontology:
Molecular function: acetylglucosaminyltransferase activity; beta-1,3-galactosyl-O-glycosyl-glycoprotein beta-1,6-N-acetylglucosaminyltransferase activity; N-acetyllactosaminide beta-1,6-N-acetylglucosaminyltransferase activity; acetylgalactosaminyl-O-glycosyl-glycoprotein beta-1,6-N-acetylglucosaminyltransferase activity; glycosyltransferase activity; UDP-glycosyltransferase activity
Biological process: carbohydrate metabolic process; protein O-linked glycosylation; protein O-linked glycosylation via N-acetyl-galactosamine
Cellular component: extracellular exosome; Golgi membrane; membrane
Genetic constraint (gnomAD): Loss-of-function variants: 3 observed, 3.82 expected, observed/expected ratio (o/e) 0.78, 90% interval 0.35 to 1.74. That is too few expected variants to judge how well the gene tolerates losing a copy. Missense variants: 684 observed, 543.17 expected, observed/expected ratio (o/e) 1.26, 90% interval 1.18 to 1.34. Synonymous variants: 264 observed, 201.96 expected, observed/expected ratio (o/e) 1.31, 90% interval 1.18 to 1.45.
Homologues: Orthologues: chimpanzee GCNT3 (99% identical), macaque GCNT3 (95% identical), pig GCNT3 (83% identical), dog GCNT3 (81% identical), rabbit GCNT3 (80% identical), rat Gcnt3 (78% identical), guinea pig GCNT3 (78% identical), mouse Gcnt3 (77% identical), tropical clawed frog gcnt3 (58% identical), zebrafish gcnt3 (52% identical), Caenorhabditis elegans gly-18 (23% identical), Caenorhabditis elegans gly-15 (22% identical), and 17 more. Paralogues in human: GCNT1 (50% identical), GCNT4 (38% identical), GCNT2 (34% identical), GCNT7 (26% identical), XYLT2 (21% identical), XYLT1 (21% identical), WSCD1 (11% identical), WSCD2 (11% identical).
Diseases named in the same sentence as GCNT3 in open-access papers:
GCNT3 is named in the same sentence as 28 diseases in open-access papers, as found by Europe PMC text mining. Sharing a sentence is not in itself a finding about the gene and the disease. The quoted sentences say what the papers report.
pancreatic cancer (13 papers, 2014 to 2025). "In contrast, high GCNT3 levels predict poor outcome in pancreatic cancer and the mucinous products of this enzyme are associated with aggressive tumorigenesis." (PMID 39547084, 2025). "Aberrant GCNT3 expression was associated with increased mucin production, aggressive tumorigenesis, and reduced patient survival, while GCNT3 knock-out in pancreatic cancer cells reduced proliferation and spheroid formation." (PMID 37996891, 2023). "Specifically, Cancer cell 1 expressed Gcnt3, Mmp7, and Vsig2, which are associated with the epithelial/classical subtype of pancreatic cancer cells." (PMID 37998349, 2023). "An isoform of C2GnT, GCNT3, has been shown to overexpress in pancreatic cancer and was associated with poor patient survival." (PMID 32075174, 2020). "Further study found that GCNT3 enzyme is abnormally expressed from GEM in pancreatic cancer as compared to the pancreases under normal conditions, resulting in high mucin formation." (PMID 35409064, 2022). "Another study suggested that the downregulation of GCNT3 significantly reduced mucin biosynthesis and pancreatic cancer cell progression." (PMID 34696660, 2021). "To select suitable pancreatic cancer cells for the assay, we analyzed the expression of genes B3GNT6 (encoding β3Gn-T6) and MUC5AC, together with genes encoding core 2 synthases (GCNT1, GCNT3, and GCNT4) by qRT-PCR." (PMID 33253272, 2020). "Altogether, we have systematically analysed the role of B3GNT3, MGAT3, FUT3 and GCNT3 in pancreatic cancer and illustrated the mechanism of GCNT3 in PC." (PMID 32203219, 2020). "GCNT3 upregulation was also seen when pancreatic cancer cell lines were treated with rosemary extracts." (PMID 32075174, 2020). "Another gene, GCNT3, glucosaminyl (N-acetyl) transferase 3, is involved in colon and pancreatic cancer." (PMID 30603059, 2018). "In order to prevent mucin overexpression in pancreatic cancer, GCNT3 is used as a novel target." (PMID 36975494, 2023). "Therefore, GCNT3 is used as a novel target to inhibit the overexpression of mucin in pancreatic cancer." (PMID 35409064, 2022). "Moreover, the high expression of GCNT3 displayed an antitumor mechanism in both colorectal and pancreatic cancers." (PMID 34696660, 2021). "In summary, our results indicate that RE exerts antitumor activity on both colon and pancreatic cancers, probably through the up-regulation of GCNT3 and the down-regulation of miR-15b, and constitutes a promising therapeutic tool in the treatment of patients suffering from these diseases." (PMID 24892299, 2014). "We identified GCNT3 as a marker of IPMN transformation into invasive carcinoma and a suitable therapeutic target for pancreatic cancer treatment." (PMID 37996891, 2023). "The glycosylation process requires the participation of many glycosyltransferases and GCNT3 is a MUC1 closely related glycosyltransferase, which was overexpressed in Kras-driven mouse and human pancreatic cancer." (PMID 35970845, 2022). "After the multi-step validation, we identified B3GNT3, B4GALNT3, FUT3, FUT6, GCNT3 and MGAT3 as top-upregulated genes in aggressive pancreatic cancer cell lines Capan-1 and HPAF/CD18." (PMID 32203219, 2020). "Among these, we successfully identified the functions of B3GNT3, GCNT3, FUT3 and MGAT3 in pancreatic cancer cells." (PMID 32203219, 2020). "In human pancreatic cancer PaCa5061 cells, however, neither sLeA/X nor static E-selectin binding were significantly altered after GCNT3 depletion here." (PMID 39547084, 2025). "Further research revealed that pancreatic cancer exhibits more mucin formation due to aberrant GCNT3 enzyme expression from GEM in pancreatic cancer than the normal pancreas." (PMID 36975494, 2023).
pancreatic cancer (continued). "Furthermore, we confirmed that GCNT3 expression correlates with MUC1 and MUC5AC expression (Pearsons’ coefficient (Cor) 0,48 and 0,51 respectively) and that they were all biomarkers of worse prognosis in pancreatic cancer patients (GCNT3, HR = 1.64), (MUC1, HR = 2.56), (MUC5AC, HR = 2.04)." (PMID 37996891, 2023).
colon cancer (9 papers, 2009 to 2025). "GCNT3, the only other glycosyltransferase significantly associated with prognosis (p = 0.05), was previously identified as a member of a 15 glycosyltransferase prognostic signature in colon cancer." (PMID 33919332, 2021). "Low GCNT3 expression has been proposed as a prognostic marker that could be used to identify early-stage colon cancer patients at high risk of relapse." (PMID 32236654, 2021). "Moreover, mucin-type C2GnT (C2GnT-M) expression, encoded by GCNT3 gene, is down-regulated in early stage colon cancer in comparison to normal colon tissues." (PMID 29416702, 2018). "We previously reported that GCNT3 kd in human colon cancer HT29 cells leads to reduced sLeA expression and static E-selectin binding, presumably decreasing metastatic competence, while sLeX was enhanced." (PMID 39547084, 2025). "The results indicate that over-expression levels of GCNT3 increases from RE-1 to RE-5, thus correlating with the potency of these RE's to inhibit cell viability and induce cell death of colon cancer cells." (PMID 24892299, 2014). "Moreover, GCNT3 expression was analyzed in colon cancer cells treated with the five different RE's at the same concentration (90 μg/mL)." (PMID 24892299, 2014).
melanoma (5 papers, 2020 to 2025). A malignant, usually aggressive tumor composed of atypical, neoplastic melanocytes. "The translated MCAM protein likely becomes highly stable through glycosylation mediated by glucosaminyl (N-acetyl) transferase 3, mucin type (GCNT3), which we previously reported in melanoma; notably, GCNT3 is also highly expressed in GC." (PMID 40924339, 2025). "Recent findings provided insights into the role of β-1,3-galactosyl-O-glycosyl-glycoprotein β-1,6-N acetylglucosaminyltransferases 3 (GCNT3) in mediating melanoma progression." (PMID 34440905, 2021). "Furthermore, silencing and functional inhibition of GCNT3 were found to suppress migration of melanoma cells." (PMID 39547084, 2025). "The authors showed that silencing of GCNT3 suppresses migration and invasion of melanoma cells." (PMID 34440905, 2021). "Mechanistically, GCNT3 led to increased S100A8/A9-mediated cell migration and invasion through the stabilization and activation of melanoma cell adhesion molecule (MCAM)." (PMID 34440905, 2021).
colorectal cancer (4 papers, 2009 to 2025). A primary or metastatic malignant neoplasm that affects the colon or rectum. "Glycosyltransferase enzyme GCNT3, has been proposed as a biomarker for prognosis in colorectal cancer (CRC)." (PMID 29855486, 2018). "Interestingly, GCNT3 appears to play divergent roles in tumor progression depending on the tumor type: in colorectal cancer, GCNT3 as well as GCNT3 levels are down-regulated, low levels are linked to higher risk of relapse, and its re-expression causes growth inhibition." (PMID 39547084, 2025).
lung carcinoma (4 papers, 2020 to 2022). "Noteworthy, GCNT3 appears to exert a tumor-restraining activity in colon and pancreatic cancer and a tumor-promoting activity in gastric and lung cancers." (PMID 36555445, 2022). "Knockdown of GCNT3 has been reported to suppress lung cancer cell proliferation and mobility." (PMID 35399076, 2022). "In lung cancer, GCNT3 is up-regulated by LINC00511, which sponges its inhibitor miR-195-5p." (PMID 36555445, 2022). "Previous studies found that GCNT3 was significantly correlated with clinicopathological malignant phenotype and poor overall survival of lung cancer patients, and GCNT3 knockout inhibited epithelial mesenchymal transformation, invasion, migration, and proliferation ability of lung cancer cells." (PMID 35399076, 2022). "Therefore, we were interested in examining whether miR-195-5p links LINC00511 and GCNT3, thus exerting cancer-suppressing functions in lung cancer." (PMID 35399076, 2022). "While SPP1 has been studied extensively in lung cancer, GCNT3 has not been well-studied." (PMID 35399076, 2022). "Lung cancer also has high expression profile of GCNT3 (a gene regulating mucin synthesis), GOLM1(a gene coding for a Golgi transmembrane protein) and IGF2BP3 (a gene coding for a RNA binding protein), which are all positively correlated with malignant progression of lung cancer." (PMID 33129284, 2020).
breast carcinoma (3 papers, 2014 to 2022). "Like MUC1, breast cancer patients with overexpressed GCNT3 and GALNT5 predict worse survival, probably due to the worse drug response mediated by over-glycosylation." (PMID 35970845, 2022). "Elevation of FUT1, GCNT2, and GCNT3 expression as seen in RWPE1 cells cultured under hypoxia may similarly underlie colon and breast cancer survival responses to hypoxia and promote invasion and metastasis." (PMID 24753248, 2014).
non-small cell lung carcinoma (3 papers, 2020 to 2025). A group of at least three distinct histological types of lung cancer, including non-small cell squamous cell carcinoma, adenocarcinoma, and large cell carcinoma. "For instance, GCNT3 is a novel core mucin synthase, usually highly expressed in non-small-cell lung cancer (NSCLC) and correlated with tumor invasion." (PMID 38095636, 2023). "Likewise, down-regulation of GCNT3 by miR-302b-3p impaired migration of non-small cell lung cancer cells." (PMID 39547084, 2025).
ovarian carcinoma (3 papers, 2018 to 2023). A malignant neoplasm originating from the surface ovarian epithelium. "Aberrant expression of Glycosyltransferase enzyme GCNT3, a master regulator of mucin-specific O-Glycosylation, was associated with increased production of mucins, reduced patient survival and chemoresistance in colon and ovarian cancer." (PMID 37996891, 2023). "All these considerations led us to examine the potential relevance of GCNT3 on epithelial ovarian cancer (EOC)." (PMID 29855486, 2018). "Although our findings were highly consistent, further in vivo experiments and analysis of GCNT3 in different stages of EOC are needed to validate the role of GCNT3 in ovarian cancer." (PMID 29855486, 2018). "Our study goes in depth into the molecular basis of GCNT3 role in tumorigenesis and drug resistance, and it explores its potential role as biomarker in epithelial ovarian cancer (EOC)." (PMID 29855486, 2018).
gastric cancer (2 papers, 2025). A primary or metastatic malignant neoplasm involving the stomach. "Our findings are in line with a previous study showing that miR-BART1-5p, directly targeting GCNT3, as well as GCNT3 knockdown inhibited migration in EBV-associated gastric cancer." (PMID 39547084, 2025).
hepatocellular carcinoma (2 papers, 2019 to 2025). A malignant tumor that arises from hepatocytes. "Expression patterns of GCNT3, GDF15, and HMOX1 in Huh7 and L-02 cells after C. pilosula or A. membranaceus treatments were similar to those in hepatocellular carcinoma HepG2 cells." (PMID 30936938, 2019). "The expression patterns of GCNT3, GDF15, and HMOX1 in Huh7 and L-02 cells after treated with qi-tonifying herbs were similar to those in hepatocellular carcinoma HepG2 cells." (PMID 30936938, 2019).
prostate carcinoma (2 papers, 2025). A carcinoma that arises from epithelial cells of the prostate gland. "However, in the context of castration-resistant prostate cancer, GCNT3 products appear to play an opposing role since migration and epithelial-to-mesenchymal transition were induced after GCNT3 depletion." (PMID 39547084, 2025).
cervical cancer (1 paper, 2025). A primary or metastatic malignant neoplasm involving the cervix. "GALNT12 and GCNT3 had HRs greater than 1, indicating that they were risk factors for cervical cancer, whereas GCNT4 and NPL had the reverse effect." (PMID 40352586, 2025).
cystic fibrosis (1 paper, 2023). Autosomal recessive disorder caused by pathogenic variants in the CFTR gene (cystic fibrosis transmembrane conductance regulator), which encodes a chloride and bicarbonate channel expressed in epithelial cells, and follow the diagnosis criteria. "Talniflumate, a small molecule targeting GCNT3 and developed for cystic fibrosis treatment, can inhibit mucin-specific O-glycosylation and expression." (PMID 37996891, 2023). "Specific inhibition of GCNT3 by talniflumate, an orally available, small-molecule inhibitor and a muco-regulator, blocks mucous overproduction in patients with chronic respiratory diseases, and reduces cystic fibrosis." (PMID 37996891, 2023).
liver cancer (1 paper, 2024). An epithelial or non-epithelial malignant neoplasm that arises from the liver. "Notably, INMT, ANO1 and GCNT3 have recently been implicated in other types of cancer, which could potentially impact the outcomes of liver cancer." (PMID 39628446, 2024).
tumor (17 papers, 2011 to 2025). "Among the few studies available, GCNT3 has been linked to both tumor progression-promoting as well as -inhibiting roles depending on the tumor type, suggesting the need for further research." (PMID 39547084, 2025). "In the same study, we profiled glycosyltransferase expression levels in the different tumor cell subsets and discovered a remarkable up-regulation of the gene GCNT3, encoding a mucin-type core 2/ core 4 β1,6-N-acetylglucosaminyltransferase (GCNT3), in the sLeA/X-positive GI adenocarcinoma cells." (PMID 39547084, 2025). "Aberrant GCNT3 expression is linked to aggressive tumor behaviors in PDAC." (PMID 40164585, 2025). "GCNT3, also a top hub gene, encodes a glycosyltransferase that participates in mucin biosynthesis; mucins are glycoproteins involved in cell–cell recognition, immune response, carcinogenesis, and tumor metastasis." (PMID 39850030, 2024). "The only phenotype that was common among all tested cell lines was the reduced migratory behavior upon GCNT3 depletion while effects on tumor cell proliferation (2D) and colony forming capacity (3D) varied inconsistently between the cell lines." (PMID 39547084, 2025). "GCNT3 products inconsistently affect tumor cell proliferation and colony formation capacity but are common pro-migratory structures in GI adenocarcinoma." (PMID 39547084, 2025). "Nevertheless, tumor cell migration was consistently reduced upon GCNT3 depletion in all tested cell lines." (PMID 39547084, 2025). "Inhibiting GCNT3 reduces mucin production, weakening the protective barrier around tumor cells, improving drug delivery, and restoring immune cell activity." (PMID 40164585, 2025). "Here we show that shRNA-mediated, stable depletion of GCNT3 reduced sLeA (tumor marker CA19-9) presentation on two out of three tested human gastrointestinal adenocarcinoma cell lines, concurrently showing reduced static E-selectin binding." (PMID 39547084, 2025). "Only the non-invasive HT29 cell line, that was isolated from a primary tumor, showed GCNT3 expression (mRNA and protein)." (PMID 29855486, 2018). "On the basis of its dose-dependent induction and its reported activity as tumor suppressor, GCNT3 was selected as one of the genes potentially involved in the antitumor mechanism of action of RE." (PMID 24892299, 2014). "In addition, we considered the effects of GCNT3 depletion on tumor cell proliferation, colony-forming capacity and migration." (PMID 39547084, 2025). "•tumor cell migration is diminished by GCNT3 depletion in GI cancers." (PMID 39547084, 2025). "The upregulation of specific GSLs in GCNT3-depleted cells might reflect compensatory mechanisms or alterations in cell surface dynamics that could influence tumor cell behavior." (PMID 39547084, 2025). "In the next step, we were interested how the GCNT3 kd affected tumor cell glycosylation." (PMID 39547084, 2025). "Combining GCNT3 inhibitors with chemotherapies like gemcitabine and nab-paclitaxel may increase tumor sensitivity and address drug resistance." (PMID 40164585, 2025). "Significant effects of GCNT3 depletion on dynamic, shear-resistant tumor cell adhesion on immobilized E-selectin as well as endothelial cells were only partially and inconsistently observable as were effects on tumor cell proliferation (2D) or 3D colony formation." (PMID 39547084, 2025). "Additionally, GCNT3 inhibition may downregulate mucins like MUC1 and MUC5AC, which are linked to tumor progression and metastasis." (PMID 40164585, 2025). "Notably, GCNT4 and GCNT3 may cooperatively regulate the structure and function of glycans through synergistic effects in the O-glycosylation process, thereby influencing tumor cell adhesion, migration, and immune evasion." (PMID 40352586, 2025).